STAT4 (signal transducer and activator of transcription 4)
Diseases named in the same sentence as STAT4 in open-access papers (continued):
Sharing a sentence is not in itself a finding about the gene and the disease.
Arthritis (15 papers, 2008 to 2024). Inflammation of a joint. "Both IL-18 receptor and STAT4 deficiency have suppressed the severity of arthritis in a murine model of RA." (PMID 34630419, 2021). "A recent study reported that the T allele of rs7574865 is significantly associated with higher levels of STAT4 mRNA and protein expression in a population of patients with early arthritis." (PMID 28107378, 2017). "As with the STAT4 rs7574865 G/T polymorphisms, the enthesitis-related arthritis and presence of hepatomegaly had strong effect on the association." (PMID 25781893, 2015). "It has been demonstrated that STAT4-deficient mice display reduced manifestation of T cell-linked experimental autoimmune diseases including encephalomyelitis, arthritis, myocarditis, colitis, and autoimmune diabetes." (PMID 22729903, 2012). "Furthermore, lisofylline (LSF), which is mainly a selective inhibitor of STAT4 and used to treat autoimmune diabetes, dampens arthritis in our mouse model by reducing miR-223-associated osteoclastogenesis." (PMID 36077117, 2022). "Our data suggest that patients with early arthritis who are homozygous for the T allele of rs7574865 in STAT4 may develop a more severe form of the disease with increased disease activity and disability." (PMID 22937072, 2012). "Therefore, our objective was to elucidate how the rs7574865 variant of STAT4 modulates its mRNA expression in a population of patients with early arthritis (EA) and whether it has functional consequences." (PMID 26569609, 2015). "Silencing IL-23p19 and inhibiting STAT4 activity ameliorates arthritis by reducing miR-223 expression." (PMID 36077117, 2022). "Effect of the presence of the shared epitope and the minor rs7574865 allele in STAT4 or rs2476601 in PTPN22 on disease activity (DAS28) and disability (HAQ) in patients with early arthritis." (PMID 22937072, 2012). "Furthermore, the LSF-treated mice with CIA also showed decreased levels of miR-223 in their joints, indicating that inhibiting STAT4 activity ameliorates arthritis concomitantly with down-regulation of miR-223 and osteoclastogenesis." (PMID 36077117, 2022). "Therefore, we treated CIA mice with a STAT4-selective inhibitor LSF and observed that LSF profoundly reduced arthritis, raising the possibility that STAT4 was likely a crucial target of LSF for its anti-arthritis effect." (PMID 36077117, 2022). "Stat4 and Stat6 were found involved in osteoclastogenesis and arthritis." (PMID 32216811, 2020). "Effect of different characteristics on STAT4 mRNA levels in patients with early arthritis." (PMID 26569609, 2015). "Effect of different variables on STAT4 protein expression in patients with early arthritis." (PMID 26569609, 2015). "Additionally, other STAT4 SNPs were correlated with lupus nephritis, arthritis, and the production of anti-SSA/B autoantibodies in a Northern Han Chinese population." (PMID 22729903, 2012). "Moreover, STAT4 phosphorylation in joint cells and intracellular IL-12p35 expression in macrophages, mast cells and Gr-1+ cells were detected in WT mice with arthritis and enhanced by LPS injection." (PMID 23036692, 2012). "Certainly, STAT4 has been associated with an increased risk of RA and mice lacking STAT4 are resistant to experimental arthritis." (PMID 19693272, 2009).
colitis (15 papers, 2012 to 2024). Inflammation of the colon. "LIF protects colitis through regulating the function of lamina propria lymphocytes via the STAT4 signaling and repair function of IECs via the STAT3/YAP signaling." (PMID 32719388, 2020). "In murine models, IL-23 was, like IL-12, able to induce STAT4 activation and overexpression was followed by colitis." (PMID 33408595, 2020). "Experimental models have shown that deletion of STAT4 may lead to protection against the development of colitis." (PMID 37735396, 2023). "Moreover, STAT4 has been postulated to contribute to suppression of regulatory T cells by Th1 cells in murine colitis." (PMID 26938566, 2016). "In experimental models, deletion of STAT4 brought about a relative protection from colitis development and, conversely, STAT4 hyperactivation resulted in spontaneous development of transmural colitis with a Th1-like immunologic profile, thus resembling human CD." (PMID 26938566, 2016). "In addition, probiotic treatment or FMT can reduce the expression and secretion of inflammatory factors (such as IFN-γ, IL-12, TNF-α, IL-6, and IL-1β) to resist colitis by regulating STAT1, STAT4, or NF-κB signals." (PMID 33532501, 2021).
systemic sclerosis (15 papers, 2010 to 2024). A chronic disorder, possibly autoimmune, marked by excessive production of collagen which results in hardening and thickening of body tissues. "In line with this, the SNP of STAT4 intron 3 (rs7574865) has been found to be associated with the limited cutaneous form of systemic sclerosis." (PMID 38790215, 2024). "Within a cohort of 1855 French Caucasian individuals, the authors observed a strong association between the STAT4 rs7574865 variant and systemic sclerosis (SSc)." (PMID 38790215, 2024). "Additionally, STAT4 gene polymorphisms are at a higher risk of type 2 diabetes and systemic sclerosis, and STAT4 was regarded as diagnostic biomarker candidates and therapeutic targets for heart failure combined with depression." (PMID 36324680, 2022). "Other variants of STAT4, such as rs11889341A and rs10168266T, have been implicated in systemic sclerosis (SSc) in various studies." (PMID 39575235, 2024). "IL-35 is known to signal via STAT1 and STAT4, consequently, the molecular mechanisms of IL-35 in systemic sclerosis were adduced to IL-35 mediated influence of pro-fibrotic STAT4 clones on T cell activation, expansion as well as patterns of cytokine release." (PMID 29641433, 2018). "As one member of the STAT family involved in transducing signals in response to IL-12, STAT4 plays an integral role in the generation of inflammation during immune responses and immune-mediated diseases, such as rheumatoid arthritis, systemic lupus erythematosus, systemic sclerosis, and psoriasis." (PMID 36324680, 2022). "The known inflammatory diseases that can be linked to STAT4 include but are not limited to chronic hepatitis B (CHB), HCC, IBDs, HBV, systemic sclerosis (SSc) and type-1 Diabetes." (PMID 35158821, 2022).
Sjögren’s syndrome (14 papers, 2012 to 2025). "This case-control study aimed to examine the relationship between STAT4 single-nucleotide polymorphisms (SNPs) and primary Sjögren’s syndrome (pSS) in a female Chinese Han population, exploring potential genetic mechanisms underlying pSS susceptibility." (PMID 40772275, 2025). "The effect of polymorphisms in STAT1 and STAT4 associated with Sjögren’s syndrome in cell culture models is currently under investigation in our laboratory." (PMID 38542139, 2024). "In the previous studies, the researchers have demonstrated that STAT4 was a confirmed genetic risk factor for Sjögren’s syndrome." (PMID 23723980, 2013). "In Sjögren’s syndrome, both STAT4 up regulation due to promoter mutations and often similar up regulation of basement membrane proteins such as Lamaninα2 are a pre-defining factor." (PMID 36172593, 2013). "These over represented models rely often on other genetic factors, such as STAT4 promoter mutations in Sjögren’s syndrome, coupled with other genetic pre-dispositions such as HLA type associations." (PMID 36172593, 2013). "Our goal was to investigate the effects of epidermal growth factor (EGF) and interferons (IFNs) on signal transducer and activator of transcription STAT1 and STAT4 mRNA and active phosphorylated protein expression in Sjögren’s syndrome cell culture models." (PMID 38542139, 2024). "STAT4 mRNA expression decreased 48 h after EGF treatment in A253 cells, immortalized salivary gland epithelial cells iSGECs nSS2 (sicca patient origin), and iSGECs pSS1 (anti-SSA negative Sjögren’s Syndrome patient origin)." (PMID 38542139, 2024).
lupus nephritis (13 papers, 2010 to 2025). Glomerulonephritis in the context of systemic lupus erythematosus. "Previous studies showed that up-regulation of lipocalin-2 in SLE can promote the in vivo and in vitro differentiation of Th1 cells via the IL-12/STAT4 signalling pathway, thereby causing an immune imbalance and leading to lupus nephritis (LN)." (PMID 36249802, 2022). "The carriers of C alleles on STAT4 had higher risk of lupus nephritis (OR 2.0; 95% CI [1.14, 3.19]; p = 0.015)." (PMID 33687153, 2021). "In the case-control analysis of cohort I, four highly linked SNPs in STAT4 were associated with lupus nephritis with genome wide significance with p = 3.7×10−9, OR 2.20 for the best SNP rs11889341." (PMID 24386384, 2013). "We conclude that genetic variations in STAT4 predispose to lupus nephritis and a worse outcome with severe renal insufficiency." (PMID 24386384, 2013). "The clearest examples are the associations of a TNFSF4 SNP with lupus nephritis, and the protection conferred by STAT4 for oral ulcers." (PMID 23049788, 2012). "Clinical studies revealed that polymorphisms of STAT4 is associated with the severity of kidney disease such as IgA nephropathy, lupus nephritis and primary membranous glomerulonephritis, suggesting that the activation of STAT4 signaling pathway is involved in immune-mediated kidney diseases." (PMID 37194066, 2023). "Allele C in rs7582694 of STAT4 has a moderate correlation with risk of lupus nephritis (OR =2.0; p = 0.015); however, it has a very strong association with higher lupus nephritis grading (10.1 times more likely to develop class III or higher ISN/RPS histology grading)." (PMID 33687153, 2021). "However, some of our results were concordant in direction and magnitude as between the TNFSF4 SNP and lupus nephritis, and STAT4 SNP and protection from oral ulcers or risk to immunologic disorder." (PMID 23049788, 2012). "For instance, our term-driven analysis highlights IRF5 and STAT4 as pivotal genes linking proteinuria and skin rash in lupus nephritis (LN)." (PMID 40128671, 2025). "Increasing STAT4 protein and gene levels in SLE patients are associated with the production of anti-dsDNA and lupus nephritis." (PMID 37978415, 2023). "Studies have shown that LCN2 promotes Th1 cell differentiation in an autocrine or paracrine manner through the IL-12/STAT4 pathway, leading to lupus nephritis (LN) deterioration." (PMID 37488573, 2023). "In this study, we evaluate the variants on three genes STAT4, CDKN1A, and IRF5 and their association with lupus nephritis." (PMID 33687153, 2021). "This is, to our knowledge, the first study to elucidate the relationship between STAT4 and lupus nephritis, as well as investigating the degree of genotype–phenotype correlation in these patients." (PMID 33687153, 2021). "The results of our study show that there was a significant difference in distribution of STAT4 genotype at position rs7582694 between SLE patients lupus nephritis and controls." (PMID 33687153, 2021). "The aim of this study was to compare genetic variants from the TGFB1, IRF5, STAT4 genes and TRAF1-C5 locus with susceptibility to IgAN and lupus nephritis in two Swedish cohorts." (PMID 20479942, 2010). "Thus, in this report, we evaluate the polymorphisms of these three genes (STAT4, CDKN1A and IRF5) and their association with the phenotype of patients with Lupus nephritis." (PMID 33687153, 2021). "Interestingly, the variants on STAT4 and GTF2I loci were correlated with lupus nephritis (LN) in the various SLE ancestries." (PMID 32771030, 2020). "Allelic frequencies of STAT4, IFR5, TRAF1-C5 and TGFB1 polymorphisms in lupus nephritis against SLE patients without nephritis." (PMID 20479942, 2010).
multiple sclerosis (13 papers, 2014 to 2025). A progressive autoimmune disorder affecting the central nervous system resulting in demyelination. "Statistical analysis revealed that STAT4 rs7574865 allele G was statistically significantly more frequent in patients with ON and multiple sclerosis (MS) than in the control group (84.38% vs. 65.93%, p = 0.003)." (PMID 38202017, 2023). "Another Egyptian study showed that signal transducer and activator of transcription 4 (STAT4) polymorphism was significantly associated with multiple sclerosis in Egyptian population." (PMID 30595647, 2018). "In experimental autoimmune encephalomyelitis (EAE), a mouse model of multiple sclerosis, mice genetically deficient in the transcription factor signal transducer and activator of transcription 4 (STAT4) are resistant to disease." (PMID 26123499, 2015). "Additionally, studies have shown that the G allele of rs10181656 and the T allele of rs10168266 are associated with reduced serum STAT4 levels in age-related macular degeneration, while the rs7601754 variant has been linked to lower STAT4 levels and increased multiple sclerosis risk." (PMID 39597056, 2024). "The ability of LSF to inhibit IL-12 signaling by blocking the activation of STAT4 has been demonstrated in mouse allergic encephalomyelitis (EAE), an experimental model of multiple sclerosis." (PMID 36077117, 2022).
type 1 diabetes (13 papers, 2010 to 2025). "This association was first observed in a genetically homogeneous population, where susceptibility to type 1 diabetes was associated with a significant increase in the frequency of the STAT4 rs7574865 T allele." (PMID 39575235, 2024). "This provides evidence that STAT4 is not only disease-specific but also associated with early development of type 1 diabetes." (PMID 38202017, 2023). "A study conducted in Poland found an association between the rs7574865 polymorphism of the STAT4 gene and the risk of type 1 diabetes in a population of Polish European children." (PMID 38275379, 2023). "The T allele and GT genotype of the STAT4 rs7574865 polymorphism were statistically significantly associated with type 1 diabetes in Egyptian study patients." (PMID 38275379, 2023). "And we proved that the STAT4 (rs7574865) variant has a significant association and type 1 diabetes, and we found that the (GT) genotype is the most frequent among patients in comparison to the GG genotype in." (PMID 34342790, 2021). "This study, therefore, inspects the impact of STAT4 variants on the vulnerability of type 1 diabetes among Egyptians." (PMID 34342790, 2021). "The current study aimed to clarify the role of STAT4 (rs7574865) variant allelic and genotypic variations in the susceptibility to type 1 diabetes among Egyptians by using the real-time PCR." (PMID 34342790, 2021). "Most importantly, our SNP of interest has been found to be associated with the extensively studied, type 1 diabetes-associated STAT4 SNP rs7574865." (PMID 30044774, 2018). "A meta-analysis study reported a significant association of the STAT4 rs7574865 polymorphism with the risk of type 1 diabetes." (PMID 30044774, 2018). "STAT4 gene expression is also associated with the risk of type 1 diabetes." (PMID 38275379, 2023). "Two SNPs in the STAT4 gene and their association with type 1 diabetes were investigated." (PMID 38202017, 2023). "Researchers have found that STAT4 alleles and the same haplotypes can influence cytokine signaling and thus the development of autoimmune thyroid disease (AITD) and type 1 diabetes." (PMID 38202017, 2023). "An earlier study on mice showed that diabetes type 1 was reduced by the interruption of the STAT4 signaling pathway." (PMID 34342790, 2021). "STAT4 genotype (rs7574865 G>T) frequencies were investigated in all 200 subjects (100 type 1 diabetes patients and 100 controls) as presented in." (PMID 34342790, 2021). "According to the results of a study by Ya-ling Liang and co-authors, the STAT4 rs7574865 SNP is not only associated with RA, SS, and SLE but also slightly associated with the risk of type 1 diabetes, juvenile idiopathic arthritis (JIA), and ulcerative colitis (UC)." (PMID 38275379, 2023). "In addition, disruption of STAT4 activation prevented the development of type 1 diabetes in NOD mice completely." (PMID 35242127, 2022). "Polymorphisms present in other genes that encode for transcription factors such as Foxp3, TBX21, and STAT4 are associated with the risk of type 1 diabetes but not with type 2 diabetes." (PMID 30044774, 2018). "The STAT4 gene polymorphism is associated with increased risk for the development of early onset type 1 diabetes but not for type 2 diabetes on the island of Crete, a well-defined area with a genetically homogeneous population." (PMID 30044774, 2018). "Therefore, targeting the IL-12/STAT4 axis to suppress Th1 cell may be an effective strategy for the treatment of type 1 diabetes." (PMID 35242127, 2022). "Disruption of STAT4 activation in NOD mice reduced Th1 type cytokine production and prevented the development of spontaneous type 1 diabetes." (PMID 35242127, 2022). "Genetics have a crucial role in the susceptibility of diabetes type 1; the most common genes related to type 1 diabetes are CTLA-4, PTPN22, STAT4, STAT3, and IFIH1." (PMID 34342790, 2021).
type 1 diabetes (continued). "Although involvement of STAT4 activation has been an overlapping clinical feature for both type 1 diabetes and type 2 diabetes, the role of rs10181656 in STAT4 is not yet clear and remains to be elucidated in the Bangladeshi population." (PMID 30044774, 2018). "Protection of STAT4 activation inhibits the development of autoimmune diabetes or type 1 diabetes in non-obese diabetic mice." (PMID 30044774, 2018). "Disruption of STAT4 activation prevents spontaneous development of Type 1 diabetes in non-obese diabetic mice." (PMID 28107529, 2017).